GFI1 (growth factor independent 1 transcriptional repressor)
Diseases named in the same sentence as GFI1 in open-access papers (continued):
Sharing a sentence is not in itself a finding about the gene and the disease.
cancer (29 papers, 2012 to 2025). A tumor composed of atypical neoplastic, often pleomorphic cells that invade other tissues. "We overexpressed GFI1 in A549 and H460 cells, mixed them with cancer-associated fibroblasts (CAFs), and subcutaneously inoculated the mixed cells into BALB/c nude mice." (PMID 35819844, 2022). "Such adaptive metabolic flexibility might contribute to therapeutic resistance as well as inferior prognosis and present a significant hurdle in targeting malignant neoplasms with the GFI1-36N variant." (PMID 39857691, 2025). "Gfi1 is also implicated in cancer development, but the available data are contradictory." (PMID 32630147, 2020). "Thus, GFI1 expression was enhanced in suspended cancer cells and may be associated with the gain of anchorage independence." (PMID 35819844, 2022). "Growth factor independence 1 (Gfi1) is a DNA binding zinc finger protein, which primarily acts as a repressive modulator in cancer and hemopathy." (PMID 40787173, 2025). "We next assessed the function of GFI1 in the regulation of cancer metastasis in vivo by utilizing a mouse xenograft model." (PMID 35819844, 2022). "Consistent with the increase in ERK phosphorylation, the treatment of cells with U0126, a specific ERK signaling inhibitor, restored anoikis in GFI1-expressing cancer cells." (PMID 35819844, 2022). "RasGRP2 knockdown nearly completely blocked GFI1-induced ERK activation in suspended cancer cells and restored anoikis of A549 and H460 cells and the ability of A549 cells to form organized acini in the basement membrane." (PMID 35819844, 2022). "GFI1 expression is particularly high in SCLCs, consistent with previous findings that GFI1 expression correlates with the neuroendocrine phenotype of human cancer." (PMID 35819844, 2022). "Other DVPs for solid cancers were annotated to genes related to bladder (TBC1D12), breast (AQP12B) or lung, prostate and colorectal (GFI1) cancers." (PMID 33632303, 2021). "Decreased lamin A/C and increased Gfi‐1 and C/EBPε were also found in the granulocytic subset in the peripheral blood of human cancer patients." (PMID 31912614, 2020). "E2F1 regulates the cell cycle and is involved in cancer genesis, and the GFi-1 protein regulates hematopoiesis and oncogenesis." (PMID 31040909, 2019). "The mean expression levels for GFI1 in carcinoma cells was 4.7-fold higher than surrounding cell types (0.33 vs 0.07 signals/cell; CI 0.08 – 0.44, P = 0.009)." (PMID 30858927, 2019). "GFI1 promotes the detachment of cancer cells from the substrate." (PMID 35819844, 2022). "To generalize this finding, we analyzed GFI1 expression in other types of cancer." (PMID 35819844, 2022). "The function of GFI1 in lung cancer cells is to promote dissemination of cancer cells from their primary site, similar to its physiological function of promoting dissemination of hematopoietic progenitor cells from their developmental niche during hematopoiesis." (PMID 35819844, 2022). "Despite the number of studies showing the loss of Gfi1 expression in cancer, there is no studies about the cellular processes promoting its silencing." (PMID 32630147, 2020). "Thus, GFI1 facilitated cancer cell detachment from substrate." (PMID 35819844, 2022). "In this study, we identified GFI1, a hematopoietic transcription factor known to drive the transition from adherent endothelial cells to suspended hematopoietic cells during early hematopoiesis, as a key factor endowing epithelial cancer cells with anchorage independence." (PMID 35819844, 2022).
cancer (continued). "We explored the underlying mechanism by which GFI1 regulates the transcriptional program, promoting detachment, anoikis resistance, and metastasis, and we evaluated its clinical implications in predicting sensitivity to ERK signaling inhibitors in cancer treatment." (PMID 35819844, 2022). "As a third test of anchorage sensing, we examined the effect of GFI1 on anchorage-independent proliferation and found that GFI1-expressing cancer cells (A549-GFI1, H460-GFI1, H1155) formed significantly more colonies in soft agar than GFI1-negative cancer cells (A549, H460, H1155-GFI1-KO)." (PMID 35819844, 2022). "Therefore, discovery of certain drug targets GFI1 for proteasomal degradation by IRF2BP2 might be an effective anti-cancer strategy." (PMID 34351909, 2021). "Moreover, because GFI1 can modulate the levels of specific bioactive lipid components that can modify cancer cell fate, this suggests that targeting GFI1 may also provide a new therapeutic approach for other types of aggressive cancers expressing high levels of c-Myc." (PMID 35159039, 2022). "Cancer driver genes namely CBL, GFI1, RASGRF2 and ELK3 were significantly down-regulated and associated with the significantly down-regulated lncRNAs -T216482, -T334719, -T217484 and -T265137 respectively." (PMID 31324852, 2019). "Thus, GFI1 activated the ERK pathway through RasGRP2 upregulation and consequently conferred cancer cells with anchorage independence." (PMID 35819844, 2022). "However, GFI1-induced substrate detachment escapes anoikis because GFI1 concomitantly upregulates RasGRP2, which in turn activates Rap1 and its downstream ERK signaling pathway to ensure survival of detached cancer cells." (PMID 35819844, 2022). "Two factors can be selected for in rearrangement-driven cancers: oncogenic biochemical function in the case of a resulting fusion protein and aberrant expression levels of a proto-oncogene (such as MYC or GFI1) via enhancer hijacking." (PMID 32416589, 2020). "This analysis showed that mean GFI1 and TNFRSF11A mRNA expression levels within carcinoma cells were significantly higher compared to other cell types (F = 14.86, P = 1.89E-08 and F = 10.27, P = 1.11E-06), including normal epithelial cells, stromal fibroblasts and lymphocytes." (PMID 30858927, 2019). "A strong increase in invasive capacity was also observed in cells over-expressing LTBR and YWHAE and to a lesser degree SNAI3 and GFI1, indicating that all these genes can drive EMT in more than one model system and have the potential to promote invasiveness of carcinomas." (PMID 27876705, 2016). "GFI1, TCF3 and BRCA1are the well-studied in development and cancer." (PMID 24421884, 2014). "Additionally, we also detected more infiltrated HLA-I–positive human cancer cells by immunostaining in the lung tissue sections in mice bearing GFI1-expressing cancer cells than in those bearing GFI1-negative cancer cells." (PMID 35819844, 2022). "Our studies unveiled a mechanism by which carcinoma cells hijacked a hematopoietic factor to gain anchorage independence and suggested that the intervention of ERK signaling may suppress metastasis and improve the therapeutic outcome of patients with GFI1-positive lung cancer." (PMID 35819844, 2022). "Similarly, GFI1 is prone to hypermethylation in cancer but not in AML and is vital for normal hematopoiesis; mice and humans lacking functional GFI1 are neutropenic suggesting that GFI1 functions in myleopoiesis and is expressed in the cells from which AMLs originate." (PMID 23034185, 2012).
infection (9 papers, 2016 to 2026). The state of being infected such as from the introduction of a foreign agent such as serum, vaccine, antigenic substance or organism. "Together, these data show that GFI1 is rapidly downregulated in activated CD8+ T cells after infection and is selectively maintained in TM cell subsets." (PMID 40374731, 2025). "(C) Images of MEFs reprogrammed with Six1, Atoh1, Pou4f3, and Gfi1 (SAPG) fixed at 14 days post infection (dpi)." (PMID 32602462, 2020). "Similarly, tamoxifen-mediated GFI1 ablation in R26creERT2/+Gfi1fl/fl at day 15 post LCMVc13 infection led to reduced R26creERT2/+Gfi1fl/fl CD8+ T cell persistence." (PMID 40374731, 2025). "Tracking the temporal dynamics of GFI1 expression early in infection using Gfi1tdTomato/+ P14 CD8+ T cells showed that GFI1-tdTomato expression was significantly downregulated on day 2 and day 3 in P14 T cells isolated from spleen and mesenteric lymph nodes (mLN), respectively." (PMID 40374731, 2025). "Deletion of GFI1 led to reduced proliferation and progressive loss of memory T cells, which in turn resulted in failure to maintain antigen-specific CD8+ T cell populations following infection with chronic lymphocytic choriomeningitis virus or murine cytomegalovirus." (PMID 40374731, 2025). "Following the initial downregulation of GFI1-tdTomato expression after LCMV infection, GFI1-tdTomato subsequently increased between day 7 and day 21 for LCMVArm infection but remained low following LCMVc13 infection." (PMID 40374731, 2025). "Following infection, CD8+ T cells showed a significant downregulation of GFI1-tdTomato expression." (PMID 40374731, 2025). "During human cytomegalovirus (HCMV) infection process, study shows that EZH2 and its regulators Jumonji domain‐containing proteins JARID2 and KDM2B repress growth factor independence 1 (GFI1), GFI1 acts as a transcriptional repressor of the HCMV immediate‐early promoter (MIEP)." (PMID 33759287, 2021). "Thus, calcineurin signaling was not essential to GFI1 regulation, and infection-induced inflammation was sufficient for GFI1 downregulation." (PMID 40374731, 2025).
hematologic neoplasms (1 paper, 2022). "Moreover, it would be interesting to explore in more detail whether the therapeutic approach described in this manuscript is transferable to other hematologic neoplasms expressing the GFI1-36N variant." (PMID 36003783, 2022).
GFI1 also shares sentences with these, for which no sentence is quoted: multiple myeloma (7 papers); T-cell acute lymphoblastic leukaemia (3); autism (2); lymphopenia (2); neuroblastoma (2); adenocarcinoma (1); Allergy (1); anemia (1); Ataxia (1); Autoimmunity (1); bacterial infection (1); blood disorders (1); bronchiectasis (1); cerebellar tumors (1); colon tumours (1); coronary artery disease (1); Cyclic neutropenia (1); eczema (1); fungal infections (1); glioblastoma (1); Hearing impairment (1); hematopoietic cancers (1); inflammatory bowel disease (1); liver cancer (1); multiple sclerosis (1); myeloproliferative neoplasm (1); myocardial inflammation (1); neuroendocrine lung tumors (1); neuroendocrine tumor (1); non-small cell lung carcinoma (1).
A further 11 diseases each share a sentence with GFI1 in 1 paper.